ANKHD1 (ankyrin repeat and KH domain containing 1)
Description:
May play a role as a scaffolding protein that may be associated with the abnormal phenotype of leukemia cells. Isoform 2 may possess an antiapoptotic effect and protect cells during normal cell survival through its regulation of caspases.
Synonyms: KIAA1085; MASK; VBARP; PP2500; FLJ20288; FLJ11979; FLJ10042; FLJ14127; MASK1
Tractability: PROTAC: ubiquitination databases record sites on it; its protein half-life has been measured.
Gene: Protein-coding gene on chromosome 5 (140,401,660 to 140,541,168, forward strand). Ensembl gene ENSG00000131503.
Subcellular location: Cytoplasm
Gene Ontology:
Molecular function: protein binding; RNA binding; nucleic acid binding
Biological process: innate immune response
Cellular component: cytoplasm; nucleus
Genetic constraint (gnomAD): Loss-of-function variants: 30 observed, 228.41 expected, observed/expected ratio (o/e) 0.13, 90% interval 0.097 to 0.18. The upper end of that interval is the gene's LOEUF score, 0.18, which puts it in group 1 of 6, group 1 being the genes least tolerant of losing a copy. Missense variants: 2,249 observed, 3,140.1 expected, observed/expected ratio (o/e) 0.72, 90% interval 0.69 to 0.74. Synonymous variants: 1,074 observed, 1,151.6 expected, observed/expected ratio (o/e) 0.93, 90% interval 0.89 to 0.98.
Homologues: Orthologues: chimpanzee EIF4EBP3 (99% identical), macaque EIF4EBP3 (98% identical), dog ANKHD1 (97% identical), pig ANKHD1 (96% identical), rabbit ANKHD1 (94% identical), mouse Ankhd1 (93% identical), rat Ankhd1 (93% identical), guinea pig ANKHD1 (86% identical), tropical clawed frog ankhd1 (72% identical), zebrafish ankhd1 (71% identical). Paralogues in human: ANKRD17 (61% identical).
Diseases named in the same sentence as ANKHD1 in open-access papers:
ANKHD1 is named in the same sentence as 32 diseases in open-access papers, as found by Europe PMC text mining. Sharing a sentence is not in itself a finding about the gene and the disease. The quoted sentences say what the papers report.
multiple myeloma (5 papers, 2016 to 2023). "Furthermore, in multiple myeloma cells, ANKHD1 has been associated with promoting cell growth and division." (PMID 37629022, 2023). "Early histochemical studies into the localisation of ANKHD1 were performed in a range of cell types, including HeLa cells, multiple myeloma cell lines and leukaemia cell lines." (PMID 37629022, 2023). "The human homolog of Mask, ANKHD1, is expressed at relatively high levels in acute leukemia cells, multiple myeloma cells and prostate cancer cells." (PMID 34553767, 2021). "In human multiple myeloma cell lines, ANKHD1 can act on the promoter region of the cyclin-dependent kinase inhibitor p21 to upregulate the proliferation of multiple myeloma cells and affect the cell cycle progression." (PMID 34235216, 2021). "Studies have demonstrated a role for ANKHD1 in promoting cell cycle progression/proliferation in renal, multiple myeloma and prostate cancer cells and in promoting hepatocellular carcinoma metastasis." (PMID 32245826, 2020). "Furthermore, increases in migration and invasiveness of cancer cells demonstrating high expression of ANKHD1 has also been described in hepatocellular carcinoma, breast cancer, non-small-cell lung cancer and multiple myeloma cells." (PMID 37629022, 2023). "Additionally, many of the roles of ANKHD1 in cancer were identified in the cytoplasm including multiple myeloma and leukaemia cell lines." (PMID 37629022, 2023). "ANKHD1 function in monocytes is unknown, but it is highly expressed in acute leukemia, multiple myeloma, and prostate cancer and may support proliferation and cell cycle progression of cancer cells." (PMID 27903268, 2016). "Moreover, ChIP has also suggested that ANKHD1 may physically interact with the p21 promoter region in multiple myeloma cell lines —suggesting two potential mechanisms of ANKHD1 and p21 interaction." (PMID 37629022, 2023).
prostate carcinoma (5 papers, 2016 to 2023). A carcinoma that arises from epithelial cells of the prostate gland. "Increased levels of ANKHD1 are also reported in prostate cancer cells, resulting in delayed cell cycle progression through the S phase and enhanced tumorigenicity in xenografts." (PMID 37629022, 2023). "In prostate cancer cell lines, ANKHD1 is a positive regulator of YAP1 and promotes cell growth and cell cycle progression by promoting cyclin A." (PMID 34235216, 2021). "Silencing of ANKHD1 leads to the downregulation of YAP1 and decreases prostate cancer cell growth and progression." (PMID 37282627, 2023). "ANKHD1, a positive regulator of YAP1, is overexpressed in prostate cancer cells." (PMID 37282627, 2023). "Moreover, increased complex formation of the ANKHD1/YAP complex has been identified in numerous cancer types due to downregulation of the Hippo signalling pathway, including non-small cell lung cancer, colorectal cancer, prostate cancer, and breast cancer." (PMID 37629022, 2023).
acute leukemia (4 papers, 2016 to 2021). A clonal (malignant) hematopoietic disorder with an acute onset, affecting the bone marrow and the peripheral blood. "ANKHD1 is overexpressed in multiple malignant tumors, such as acute leukemias, renal cancer cell, and breast cancer." (PMID 30646949, 2019).
glioma (4 papers, 2022 to 2024). A benign or malignant brain and spinal cord tumor that arises from glial cells (astrocytes, oligodendrocytes, ependymal cells). "More recently, ANKHD1 was also shown to interact with the long non-coding RNA (lncRNA) LINC00346 to regulate glioma angiogenesis and with the lncRNA MALAT1 to promote resistance to radiotherapy in colorectal cancer." (PMID 37629022, 2023). "Of these 13 cancers, ANKHD1 is upregulated in specific subsets of glioma, renal cell carcinoma and leukaemia, which validates previous evidence that ANKHD1 is overexpressed in those cancer types." (PMID 37629022, 2023). "Furthermore, the promoter region of ANKHD1 was targeted by ZNF655 and formed the feedback loop of ANKHD1/LINC00346/ZNF655 that regulated the angiogenesis of adult glioma cells." (PMID 37444408, 2023). "An increase in ANKHD1 is detected in glioma-associated endothelial cells, but there are no data to show how this may affect prognosis." (PMID 37629022, 2023). "In addition, ZNF655 directly binds to the ANKHD1 promoter region to inhibit its transcription, further forming an ANKHD1/LINC00346/ZNF655 feedback loop, which can regulate glioma angiogenesis through messenger RNA decay mediated by Staufen1." (PMID 38967893, 2024).
hepatocellular carcinoma (3 papers, 2019 to 2023). A malignant tumor that arises from hepatocytes. "Since this research, the clinical features correlating with increased levels of ANKHD1 have also been examined in colorectal cancer, non-small-cell lung carcinoma, and hepatocellular cancer." (PMID 37629022, 2023).
leukemia (3 papers, 2020 to 2023). A malignant (clonal) hematologic disorder, involving hematopoietic stem cells and characterized by the presence of primitive or atypical myeloid or lymphoid cells in the bone marrow and the blood. "Higher levels of ANKHD1 (protein and mRNA) are observed in leukaemia cell lines and (mRNA only) are observed in primary acute leukaemia samples." (PMID 37629022, 2023). "In the K562 line of leukemia cells, ANKHD1 acts as a skeleton protein and affects its malignant phenotype by interacting with SHP2." (PMID 34235216, 2021). "In humans, ANKHD1 and SHP2 have been demonstrated to physically interact via coimmunoprecipitation assays in leukaemia cell lines K562 and LNCap, and it was suggested that ANKHD1 may be functioning as an adaptor protein." (PMID 37629022, 2023). "ANKHD1 was identified in a screen for proteins which interact with SH2-containing protein–tyrosine phosphatase (SHP2), a tyrosine phosphatase overexpressed in primary leukaemia cells and leukaemic cell lines —an interaction that demonstrated the role of ANKHD1 in leukaemia." (PMID 37629022, 2023). "However, ANKHD1 did not coimmunoprecipitate with SHP2 in other leukaemia cell lines (KG1, HL60, Daudi and Jurkat) despite them presenting with high levels of SHP2 protein expression, potentially demonstrating this interaction may be cell-line specific." (PMID 37629022, 2023).
breast carcinoma (2 papers, 2019 to 2023). "Increased levels of ANKHD1 were correlated with a reduction in relapse-free survival, but the extent differs based on the breast cancer subtype." (PMID 37629022, 2023).
melanoma (2 papers, 2011 to 2024). A malignant, usually aggressive tumor composed of atypical, neoplastic melanocytes. "All proteins were detected in melanoma patient samples, two of which were exclusive to these patients (HIST1H1E, ANKHD1)." (PMID 39405606, 2024).
renal cell carcinoma (2 papers, 2023 to 2025). "ANKHD1 expression (protein and mRNA) is upregulated early in the kidneys of patients with renal cell carcinoma." (PMID 37629022, 2023). "The novel finding of Ankhd1 expression in ADPKD suggests its potential role in cystogenesis and disease progression, paralleling its known oncogenic functions in renal cell carcinoma and other cancers." (PMID 40457431, 2025). "While it was already known that ANKHD1 is highly expressed in kidneys of patients with renal cell carcinoma, whether it was expressed in normal kidneys without disease and in polycystic kidneys was previously unknown." (PMID 40457431, 2025).
Alzheimer disease (1 paper, 2025). A progressive, neurodegenerative disease characterized by loss of function and death of nerve cells in several areas of the brain leading to loss of cognitive function such as memory and language. "In this study, we provide evidence that ANKHD1 promotes autophagy in cultured cells and modestly alleviates neuropathology in a mouse model of Alzheimer’s disease." (PMID 40806649, 2025).
chronic kidney disease (1 paper, 2025). Impairment of the renal function secondary to chronic kidney damage persisting for three or more months. "Therefore, while here we explore the role of ANKHD1 in ADPKD, we propose that may have additional roles in diseases beyond ADPKD, such as in both acute and chronic kidney diseases." (PMID 40457431, 2025).
Cognitive Deficits (1 paper, 2025). "In contrast, the absence of cognitive impairment in male PS19 mice at this age precluded evaluation of ANKHD1’s protective effects in males." (PMID 40806649, 2025).
colorectal cancer (1 paper, 2023). A primary or metastatic malignant neoplasm that affects the colon or rectum. "Colorectal cancer cells show increased levels of ANKHD1 and are associated with an increase in epithelial-to-mesenchymal transition, allowing increased cell mobility, possibly linking ANKHD1 to increased migration and the invasion of cancer cells." (PMID 37629022, 2023).
colorectal tumors (1 paper, 2022). "A significant positive correlation was found between ANKHD1 and YAP1 in the tested colorectal tumors: 70% (84 of 120) of tumors with high expression of ANKHD1 also showed high YAP1 levels (bottom)." (PMID 35110552, 2022). "In addition, upregulated ANKHD1 was observed in 81% (120 of 148) of colorectal tumors." (PMID 35110552, 2022). "To further determine the relevance of ANKHD1 and YAP1, we evaluated YAP1 protein expression in colorectal tumors as well as normal tissues by IHC on tissue microarrays." (PMID 35110552, 2022).
cyst (1 paper, 2025). A sac-like closed membranous structure that may be empty or contain fluid or amorphous material. "We show that loss of function of either human or murine ANKHD1 leads to smaller kidneys, reduced cyst size and improved renal function." (PMID 40457431, 2025). "Its reduction leads to attenuated cyst formation and improved renal parameters, highlighting ANKHD1 as a potential therapeutic target for ADPKD." (PMID 40457431, 2025). "Immunohistochemical analysis revealed widespread Ankhd1 throughout the kidney, with high levels in cyst lining cells of Pkd1nl/nl mice." (PMID 40457431, 2025). "We find that ANKHD1 protein localises in cyst lining cells of both aquaporin-1 and 2 (AQP1-AQP2) positive cysts." (PMID 40457431, 2025). "ANKHD1-silenced cells formed significantly smaller cysts in both cell lines, as measured by cyst diameter, indicating overall reduced spheroid size." (PMID 40457431, 2025). "By modulating the Cyclin D1/CDK4/Rb axis and p19 regulation, ANKHD1 inhibition could potentially slow cyst growth and disease progression." (PMID 40457431, 2025). "Moreover, environmental factors such as diet and housing conditions can also impact kidney function and cyst development obscuring any specific effects of ANKHD1." (PMID 40457431, 2025). "Collectively, these results underscore the critical role of ANKHD1 in driving cell cycle dynamics in ADPKD and highlight its potential as a therapeutic target in modulating cyst growth." (PMID 40457431, 2025).
lung carcinoma (1 paper, 2022). "Herein, we tested the directly physical interaction between ANKHD1 and YAP1, suggesting that ANKHD1 directly affects YAP1 transcriptional activity rather than triggers the Hippo pathway, which is consistent with a previous report in lung cancer." (PMID 35110552, 2022).
pancreatic cancer (1 paper, 2022). "In our study, we found that the overexpression of ANKHD1 significantly inhibited p21 expression in pancreatic cancer." (PMID 34743406, 2022). "In our study, we demonstrated that PTEN could induce p21 expression via interacting with ANKHD1 and enhancing the binding degree of ANKHD1 to the p21 promoter in pancreatic cancer cells." (PMID 34743406, 2022). "Our study also identified a novel mechanism by which PTEN induced p21 expression in pancreatic cancer cells; this could contribute to the interaction with ANKHD1 and inhibit binding to the p21 promoter of ANKHD1." (PMID 34743406, 2022). "Furthermore, the exploration of ANKHD1 inhibitor treatment could provide novel therapy strategies for pancreatic cancer, especially in combination with MDM2 inhibitor treatment, which should be verified by further research." (PMID 34743406, 2022). "Therefore, the regulation of p21 by PTEN was dependent on ANKHD1 in pancreatic cancer cells." (PMID 34743406, 2022). "Therefore, ANKHD1 might also be a novel therapeutic target of pancreatic cancer." (PMID 34743406, 2022). "Taken together, these findings indicate that ANKHD1 and MDM2 might be a novel therapeutic target in pancreatic cancer." (PMID 34743406, 2022). "Taken together, our results indicate that ANKHD1 and MDM2 might be novel therapeutic targets in pancreatic cancer." (PMID 34743406, 2022).
pancreatic ductal adenocarcinoma (1 paper, 2023). An infiltrating adenocarcinoma that arises from the epithelial cells of the pancreas. "Premature termination of the ANKHD1 protein due to a nonsense mutation (E2410*) was correlated with Pancreatic Ductal Adenocarcinoma." (PMID 37629022, 2023).
polycystic kidneys (1 paper, 2025). "Since the development of cysts in ADPKD is at least in part due to increased cell proliferation and ANKHD1 is a cancer associated pro-proliferative protein we hypothesised that ANKHD1 has a major role in controlling proliferation in the polycystic kidney." (PMID 40457431, 2025). "However, the specific role of ANKHD1 in regulating proliferation in polycystic kidneys remains unknown." (PMID 40457431, 2025). "Here we show that ANKHD1 is indeed expressed in non-cancer kidney tissue, and its expression is high in the polycystic kidney." (PMID 40457431, 2025).
Renal cyst (1 paper, 2025). A fluid filled sac in the kidney. "We suggest that by reducing the expression levels of ANKHD1, we could achieve slower proliferation, reduce the size of the renal cysts and help slow down kidney function decline in patients with ADPKD." (PMID 40457431, 2025).
tauopathies (1 paper, 2025). "Thus, future strategies aimed at enhancing ANKHD1 expression—either globally or in targeted brain regions—may be necessary to fully assess its therapeutic capacity in the context of tauopathy." (PMID 40806649, 2025).
cancer (12 papers, 2015 to 2025). A tumor composed of atypical neoplastic, often pleomorphic cells that invade other tissues. "Accumulating evidence has demonstrated that dysregulated ANKHD1 serving as an oncoprotein is associated in various malignant tumors." (PMID 35110552, 2022). "This works aligns with previous work showing ANKHD1’s role in regulating proliferation in cancer, where ANKHD1 was found to control cell cycle progression via miRNA interactions requiring its KH domain." (PMID 40457431, 2025). "To investigate this, we examined the expression and function of the Ankyrin Repeat and single KH Domain 1 (ANKHD1), which positively regulates proliferation in cancer, yet its role in ADPKD is unexplored." (PMID 40457431, 2025). "Studies into the role of ANKHD1 in cancer cell lines demonstrate a crucial role in driving uncontrolled cellular proliferation and growth, enhanced tumorigenicity, cell cycle progression through the S phase, and increased epithelial-to-mesenchymal transition." (PMID 37629022, 2023). "Elevated ANKHD1 resulted in poorer prognosis, more aggressive growth, and a decrease in patient survival in numerous cancer types." (PMID 37629022, 2023). "This review aims to gather the current knowledge about ANKHD1 and explore its molecular properties and functions, focusing on the protein’s role in cancer at both a cellular and clinical level." (PMID 37629022, 2023). "The results showed that the ANKHD1 level were higher in pericarcinomatous tissues than in cancer tissues." (PMID 36171217, 2022). "ANKHD1 were widely expressed in normal tissues and cancer cell lines at different levels, and the aberrant expression of ANKHD1 has been reported in some types of cancer." (PMID 34743406, 2022). "Studies into the role of ANKHD1 in cancer have identified it as a key driver of uncontrolled cellular proliferation, enhanced tumorigenicity, accelerated cell cycle progression, and increased epithelial-to-mesenchymal transition, all of which contribute to enhanced tumor thriving." (PMID 40806649, 2025). "Given ANKHD1’s pro-survival function in cancer cells and its high sequence homology with Mask, we hypothesize that ANKHD1 exerts a conserved neuroprotective role like its Drosophila homolog mask." (PMID 40806649, 2025). "A summary of the cellular and clinical functions of ANKHD1 in cancer." (PMID 37629022, 2023). "In addition, the overall survival of patients with high ANKHD1 mRNA expression levels is poorer than those with low mRNA expression ANKHD1 levels between 200 and 300 months after diagnosis in a range of cancer types." (PMID 37629022, 2023). "Previous studies had shown the evidence of ANKHD1 in the malignant phenotype of cancer cells, including promoting cancer cell proliferation, migration, invasion, and tumorigenesis, by positively regulating of YAP1, JAK/STAT, and STMN1, and negatively regulating p21." (PMID 34743406, 2022). "RT-PCR and WB were used to detect the expression of ANKHD1 in carcinoma and para-carcinoma tissues." (PMID 36171217, 2022). "Five cryptically spliced genes (ANKHD1, ATM, FOXP1, MAP3K7, and TTI1), identified in previous transcriptomic analyses in SF3B1-mutated patients, were analyzed in different cancer types." (PMID 33585229, 2020). "In recent years, ANKHD1 has been shown as a potential biomarker in various cancers." (PMID 30646949, 2019). "In light of our previous findings and the known importance of AS events in carcinogenesis and tumour-progression, we checked for cancer-related splice isoforms among our candidate genes for which both transcripts were annotated as protein-coding, such as ANKHD1 in SW480 and MYO1C in SW620." (PMID 31443305, 2019). "Given that ANKHD1 overexpression is able to drive enhanced proliferation and cellular invasion of cancerous cells, it would be anticipated that overexpression of ANKHD1 may also impact cancer pathologies at a clinical level." (PMID 37629022, 2023).